SIRT1 (sirtuin 1)
Diseases named in the same sentence as SIRT1 in open-access papers (continued):
Sharing a sentence is not in itself a finding about the gene and the disease.
cognitive decline (58 papers, 2012 to 2026). "SIRT-1 plays a vital role in neuronal plasticity and shield against neuronal degeneration associated with cognitive decline." (PMID 37237920, 2023). "According to these data, topiramate’s ability to suppress hippocampal oxidative events and stimulate SIRT1/Nrf2 axis is, at least partly, engaged in rescuing the cognitive decline associated with cadmium intoxication." (PMID 37765022, 2023). "They studied the CA1 region of the hippocampus to determine if SIRT1 is protective against memory loss and cognitive decline in AD." (PMID 30532738, 2018). "This neuronal cell autonomous activity of SIRT1 is also important for neuronal plasticity, cognitive functions, as well as protection against aging-associated neuronal degeneration and cognitive decline." (PMID 25805970, 2015). "SIRT1 deficiency in microglia has been associated with cognitive decline during neurodegeneration." (PMID 40791576, 2025). "Moreover, SIRT-1 is involved in a variety of complex processes relevant to aging-associated neuronal degeneration and cognitive decline and aging, including the regulation of oxidative stress." (PMID 39061398, 2024). "Hence, this research aims to explore how SIRT1/BDNF impacts cognitive decline caused by anesthesia/surgery in aged mice." (PMID 38783169, 2024). "The scientists hypothesized that an increased expression of IL-1β is linked to memory impairments and accompanying cognitive decline, which could be caused by epigenetic changes brought on by SIRT1 deficiency (aging-induced) in microglia." (PMID 35893883, 2022). "SIRT1 role as longevity regulator is well-known, since it acts as a key molecule in neuronal plasticity, cognitive functions, as well as protection against ageing-associated neuronal degeneration and cognitive decline." (PMID 34203691, 2021). "SIRT1 is known as a longevity-associated protein and serves as a potential pharmacological target to increase the lifespan of humans and stands at the front line against cognitive decline, neurodegenerative disease, and aging." (PMID 31430865, 2019). "SIRT1 has been referred to as a longevity-associated protein that could be used as a potential pharmacological target for extending human lifespan, and it is at the forefront of the battle against cognitive decline, neurodegenerative diseases, and aging." (PMID 37580391, 2023). "The authors suggested that aging-induced SIRT1 deficiency in microglia could initiate epigenetic alterations on IL-1beta, leading to its enhanced expression that is associated with impairments in memory and related cognitive decline." (PMID 27790141, 2016). "Reduced SIRT1 and Nrf2 levels likely weaken antioxidant defenses, increasing oxidative stress that contributes to fatigue and cognitive decline." (PMID 41601525, 2026). "Crucially, the formulation also modulates key biomarkers associated with cognitive decline, reducing APP and phosphorylated tau levels (about 98% and 1.6-fold vs. H2O2) while increasing Sirtuin 1 and Nrf2 expression (about 3.6-fold and 3-fold vs. H2O2)." (PMID 40807615, 2025). "The SIRT1/PGC1α pathway plays a crucial role in brain health, serving as a key network in combating cognitive decline." (PMID 41140914, 2025). "Inhibition of miR-181a-5p suppresses astrocyte and microglial activation by upregulating SIRT1, which plays a role in suppressing seizures and ameliorating cognitive decline in TLE patients." (PMID 40791576, 2025). "Treating 3xTg-AD mice with SLAB51 (a probiotic mix) activated the NAD+/SIRT1 (Sirtuin-1) pathways, boosted neuronal autophagy, reduced Aβ aggregates, and slowed cognitive decline." (PMID 40564109, 2025). "Lactate, an exercise-induced myokine, penetrates the blood–brain barrier (BBB) and triggers the BDNF pathway, potentially safeguarding against cognitive decline and neurodegeneration through the SIRT1/PGC1/FNDC5 pathway." (PMID 40426650, 2025).
cognitive decline (continued). "Previous study showed that resveratrol significantly alleviated hippocampal neuroinflammation by activating SIRT1 and prevented cognitive decline after abdominal surgery in aged rats." (PMID 38783169, 2024). "Mean plasma SIRT1 levels of the cognitive decline group were 1.85 (1.01-2.96) ng/mL, compared with 2.01 (1.38-3.47) ng/mL for the cognitively unchanged group, which was close to statistical significance (P = 0.059)." (PMID 38559694, 2024). "The latest study has revealed that aerobic exercise combined with chlorogenic acid exerts neuroprotective effects and reverses cognitive decline in the AD model mice (APP/PS1) through the SIRT1/PGC-1α/PPARγ signaling pathway." (PMID 39022312, 2024). "The cognitive decline observed was accompanied by significant changes in the alternative splicing of the TrkB receptor and Sirt1 protein in females." (PMID 35563336, 2022). "We recently showed that old female mice exhibiting age-related cognitive decline had a larger amount of the 50 kD Sirt1." (PMID 35563336, 2022). "In AD model animals, overexpression of Sirt-1 slowed cell death, neurodegeneration, and cognitive decline." (PMID 33834065, 2021). "Similar to the role of miR-200 family in regulating SIRT1 in metabolic disease, it also plays a role in the regulation of SIRT1 in cognitive decline." (PMID 34690698, 2021). "In fact, miR-34c/Sirt1 post-transcriptional negative regulation was also described in a mouse model of cognitive decline." (PMID 33569381, 2020). "It was reported previously that decrease of microglial SIRT1 contributed to aging-related neurodegeneration and cognitive decline." (PMID 33381265, 2020). "Taken together, these findings raised the possibility that the hippocampal SIRT1 reduction induced tau acetylation and consequently contributed to cognitive decline following anesthesia and surgery." (PMID 33381265, 2020). "Overexpression of SIRT1 provided protection against pathological protein aggregation and cognitive decline in an AD model while improving cognitive function in the wild-type control." (PMID 30532738, 2018). "Resveratrol suppresses cognitive decline through promoting Sirt1 expression or the activation of Sirt1." (PMID 30243024, 2018). "Edible bird's nest (EBN) is traditionally used to improve general wellbeing, and in this study, we evaluated its effects on SIRT1 expression in the hippocampus and implications on ovariectomy-induced memory and cognitive decline in rats." (PMID 29104731, 2017). "Moreover, baicalein exerts a neuroprotective effect against cognitive decline through the SIRT1-mediated Notch1 pathway, which in turn improves angiogenesis and suppresses neuroinflammation." (PMID 40290868, 2025). "Additionally, autophagy-mediated ADAR1 degradation and ADAR1/SIRT1 pathway are essential for propofol-induced senescence and cognitive decline." (PMID 41429887, 2025). "That is, the SIRT1/PGC1α pathway serves as a key network against cognitive decline." (PMID 41140914, 2025). "Lowered SIRT1 levels in microglia upregulate IL-1β, leading to cognitive decline in mice with age." (PMID 40363789, 2025). "However, even in the presence of damage and inflammation, activation of SIRT1 can protect the brain from neural injury and cognitive decline." (PMID 39022312, 2024). "Moreover, the observed DPG-induced SIRT1 upregulation has been characterized to attenuate cognitive decline via curtailing tau phosphorylation and amyloid plaque accumulation." (PMID 38002000, 2023). "Exercise-induced PGC-1α was accompanied by an increase in BDNF release, indicating that swimming exercise could ameliorate cognitive decline through SIRT1/PGC-1α/BDNF." (PMID 36999158, 2023).
cognitive decline (continued). "Interestingly, old mice, exhibiting age-related cognitive decline, had a larger amount of the 50 kD SIRT1 isoform compared to the longer, 100 kD Sirt1 isoform." (PMID 35563336, 2022). "In summary, this study demonstrated that prolonged aerobic exercise can reverse the cognitive decline caused by T2DM, which may be related to the activity of AMPK/SIRT1 and the inhibition of JAK2/STAT3 signalling in T2DM mice." (PMID 35578689, 2022). "Aerobic exercise may also be used to prevent synapse formation disorders and cognitive decline through enhancing the AMPK/SIRT1 and inhibiting the JAK2/STAT3." (PMID 35578689, 2022). "Decreased levels of SIRT-1 in microglia contribute to cognitive decline and neuroinflammation." (PMID 34716387, 2021). "Indeed, HBO preconditioning increased the expression of SIRT1, Nrf-2, and HO-1 and ameliorated memory dysfunction in additional models of cognitive decline, and SIRT1 was also shown to play a role in recovery after middle cerebral artery occlusion in rats." (PMID 34680155, 2021). "CR may delay cognitive decline in mice by modulating the SIRT1/mTOR signaling pathway and by activating SIRT1 and suppressing mTOR signaling." (PMID 34552957, 2021). "Pretreatment with resveratrol, a natural activator of SIRT1, mitigated SIRT1 suppression, further downregulated the level of tau acetylation and hyperphosphorylation in the hippocampus and consequently mitigated the cognitive decline of the aged POCD model." (PMID 33381265, 2020). "Indeed, SIRT1 has recently been shown to play a role in normal cognitive function and synaptic plasticity, counteracting cognitive decline and neurodegenerative disease in aging." (PMID 32397504, 2020). "Taken together, these studies show that SIRT1 may be a critical regulator of aging, exerting a pivotal role in memory and behavior, and is closely related to cognitive decline in aging and neurodegenerative diseases." (PMID 31430865, 2019). "Direct in vivo evidence supported the link between SIRT1 and improvement of cognitive decline." (PMID 29164153, 2017). "We suggest that the protection against endothelial senescence in the hippocampus through up-regulation of testosterone and SIRT1 could contribute to a novel therapeutic strategy against cognitive decline with aging." (PMID 22238626, 2012). "Moreover, Sirt1 protects against aging-related neuronal degeneration and cognitive decline." (PMID 35096297, 2021). "In the context of the neuronal relevance of mitochondrial functions, we hypothesize that it is possible to delay onset of age-related cognitive decline through metabolic SIRT1-dependent adaptation and improvement of mitochondrial function mediated by TRPV1 control." (PMID 30050571, 2018). "The present study demonstrated that testosterone and SIRT1 interacts with each other and inhibited the senescence of hippocampal vascular and neuronal cells, suggesting that testosterone replacement therapy is a treatment option for cognitive decline with aging." (PMID 22238626, 2012). "Unprecedented reversal of the senescent hippocampal changes and vascular protection may justify exploration of a neuronal rejuvenation strategy by utilizing testosterone for the prevention of cognitive decline with aging, particularly through up-regulation of eNOS/SIRT1." (PMID 22238626, 2012). "The transcription factor Sirtuin1 (Sirt1) can activate PGC-1α by deacetylation, resulting in increased synthesis and secretion of synaptic proteins in the brain, and thereby mitigating cognitive decline." (PMID 38231482, 2024). "Resveratrol, an activator of SIRT1, can activate SIRT1 in aged POCD mice, reverse the decrease of sex-determining region Y-box-2 (Sox2) induced by anesthesia/surgery and alleviating cognitive decline in aged POCD mice." (PMID 38783169, 2024).
cognitive decline (continued). "In the aged C57BL/6J mouse model of IR induced by a high-fat diet, SIRT1 improved mitochondrial function via the SIRT1-AMPK-PGC-1α axis and the neuronal differentiation 6 (NeuroD6)-PGC-1α-SIRT1 axis to enhance cognitive decline." (PMID 29164153, 2017). "For instance, mice lacking neuronal SIRT1 show accelerated tau accumulation and cognitive decline, whereas SIRT1 overexpression or activation reduces tau acetylation and slows the spread of tau tangles." (PMID 41031163, 2025). "However, the mechanisms of SIRT1 in cognitive decline under the condition of IR are inadequate and not in-depth and systematical, for example, a gap in the studies on mechanism of SIRT1 regulating neuronal energy metabolism and function." (PMID 29164153, 2017). "SIRT1 participates in apoptosis, autophagy, and development, as well as in metabolism and circadian rhythms; therefore, it is not surprising that SIRT1 affects more complex biological processes including aging, MCI, and cognitive decline." (PMID 29164153, 2017).
cardiomyopathy (56 papers, 2012 to 2025). A disease of the heart muscle or myocardium proper. "In transgenic SIRT1 mice, lower SIRT1 levels encouraged antioxidative activity, whereas greater levels caused cardiomyopathy, possibly as a compensatory reaction to increased antioxidant levels." (PMID 41011644, 2025). "In contrast, high levels of SIRT1 enhanced hypertrophy and apoptosis, thereby causing cardiomyopathy." (PMID 41567643, 2025). "Herein, we provide new data to support the regulatory action of apigenin on UPRmt, by identifying the Sirt1/Atf5 pathway as a central mechanism underlying apigenin's cardioprotective effects against Dox-induced cardiomyopathy." (PMID 37928261, 2023). "Our data confirmed that in the setting of on Dox-induced cardiomyopathy, Sirt1 deficiency weakens the cardioprotective actions of apigenin." (PMID 37928261, 2023). "Since the main cause of death in patients with DMD is cardiomyopathy, we also assessed the studies that demonstrated the efficacy of activating SIRT1 in heart." (PMID 34205021, 2021). "SIRT1 activation also plays protective roles against the cardiomyopathy associated with muscular dystrophy models." (PMID 27073590, 2016). "For example, moderate elevation of SIRT1 protects cardiomyocytes, and high elevation of SIRT1 decreases cardiac function and causes cardiomyopathy." (PMID 24587358, 2014). "A large number of important transcription factors or regulators implicated in cardiomyopathy have been identified as bona-fide targets of miR-22, including Purb, Hdac4, Ppara, Sirt1, and Pgc1a." (PMID 24086656, 2013). "In addition, loss of SIRT1 activity has been reported in type 1 diabetic nephropathy and cardiomyopathy." (PMID 23226517, 2012). "It has been shown that moderate SIRT1 overexpression protected the heart from oxidative stress through the increased expression of antioxidants, whereas higher SIRT1 levels induce cardiomyopathy, possibly through the induction of mitochondrial dysfunction." (PMID 40015131, 2025). "It induces calcium signaling dysregulation via the SIRT1-CaMKII-RYR2 signaling pathway, closely associated with diseases like cardiomyopathy." (PMID 41140684, 2025). "Activating the SIRT1/Nrf2 pathway helps melatonin lower oxidative stress, pyroptosis, and apoptosis in Dox-induced cardiomyopathy." (PMID 41567643, 2025). "By contrast, SIRT1 upregulation alleviated cardiac oxidative damage and diabetic vascular complications even if excessive SIRT1 overexpression induced cardiomyopathy." (PMID 38255934, 2024). "SIRT1 deficiency contributes to CMD pathogenesis and cardiomyopathy by increasing microvascular oxidative stress." (PMID 39598406, 2024). "Studies have demonstrated that the SIRT1/eNOS pathway has a beneficial effect in conditions like ischemia reperfusion, atherosclerotic processes, and cardiomyopathy." (PMID 37932729, 2023). "In sum, our work revealed that apigenin exerts therapeutic effects in mice with Dox-mediated cardiomyopathy through activation of the Sirt1/Atf5/UPRmt axis in cardiomyocytes." (PMID 37928261, 2023). "Our findings hence support the therapeutic potential of apigenin in the treatment of Dox-induced cardiomyopathy, and highlight the Sirt1/Atf5/UPRmt axis as a promising target for the design and development of drugs against Dox-related cardiotoxicity." (PMID 37928261, 2023). "To address the regulatory mechanism(s) by which apigenin activates the UPRmt during Dox-induced cardiomyopathy, we focused on the Sirt1/Atf5 pathway." (PMID 37928261, 2023). "Fisetin exerts its therapeutic effects on DOX-induced cardiomyopathy by inhibiting ferroptosis via SIRT1/NRF2 pathway activation in the rat model of DOX-induced cardiomyopathy and H9c2 cells." (PMID 37153222, 2023). "Increased ADSC function accelerates cardiac regeneration in diabetic rats with cardiomyopathy through Sirt1/p-Akt axis activation." (PMID 35328586, 2022).